MIR484 (microRNA 484)
Synonyms: hsa-mir-484; MIRN484; mir-484
Gene: MicroRNA gene on chromosome 16 (15,643,294 to 15,643,372, forward strand). Ensembl gene ENSG00000283736.
Gene Ontology:
Biological process: miRNA-mediated post-transcriptional gene silencing
Cellular component: RISC complex
Homologues: Orthologues: chimpanzee ptr-mir-484 (100% identical), macaque MIR484 (96% identical), mouse Mir484 (70% identical).
Diseases named in the same sentence as MIR484 in open-access papers:
MIR484 is named in the same sentence as 1 disease in open-access papers, as found by Europe PMC text mining. Sharing a sentence is not in itself a finding about the gene and the disease. The quoted sentences say what the papers report.
adrenocortical cancer (1 paper, 2018). "Interestingly, Mir484 has been implicated in suppressing translation of mitochondrial fission protein FIS1 and inhibited FIS1-mediated fission and apoptosis in cardiomyocytes and adrenocortical cancer cells." (PMID 29324753, 2018).